TWIST1 (twist family bHLH transcription factor 1)
Diseases named in the same sentence as TWIST1 in open-access papers (continued):
Sharing a sentence is not in itself a finding about the gene and the disease.
cancer (continued). "The ALDHhigh cells isolated from these cancers showed high gene and protein expression of stemness transcription factors Nanog, sex determining region Y-box2 (Sox2), octamer-binding transcription factor (Oct4), and twist-related protein 1 (Twist1)." (PMID 32295073, 2020). "Our recent studies suggest that the transcription factor Twist1 is also actively involved in the regulation of cancer-induced muscle wasting presumably owing to its ability to induce the expression of MuRF1 and Atrogin1, thereby causing muscle protein degradation and attendant muscle cachexia." (PMID 32655411, 2020). "Data analyses of gene expression profiles of patient samples from The Cancer Genome Atlas (TCGA) reveal a positive correlation between Twist1 and mesenchymal genes across cancers, whereas the correlation of TWIST1 with CIN and DSB genes is cancer subtype-specific." (PMID 32337580, 2020). "In addition, TWIST-1 has been reported to be up-regulated in a large number of malignant tumor playing a main role in the onset of metastasis by promoting invasiveness." (PMID 33085676, 2020). "Other signaling pathways contributing to PH pathology, including TGFβ-smad signaling, TNFα-NFkB signaling, IL661,62, and CD44-LOX signaling are known to induce Twist1 expression in cancer cells and may be involved in the mechanism." (PMID 32371931, 2020). "From a translational perspective, elevated expression of Twist1 is also detected in cancer patients with severe muscle wasting, implicating a role of Twist1 in cancer cachexia, and further providing a possible target for therapeutic attenuation of cachexia to improve cancer patient survival." (PMID 32655411, 2020). "Various EMT transcription factors have been proposed among different cancer types, including Snail, Slug, TWIST1/2, and zinc finger E-box-binding homeobox 1/2 (ZEB1/2), as they may affect transcription of E-cadherin and other EMT markers." (PMID 31963305, 2020). "Moreover, combined MYC and TWIST1 expression strongly correlated with the expression of M2 macrophage related genes in the pan-cancer TCGA data." (PMID 31933479, 2020). "Furthermore, while Twist1 overexpression shows a positive correlation with the expression levels of EMT genes, on the contrary, it shows a cancer-specific correlation with DNA DSBs or CIN-associated genes." (PMID 32337580, 2020). "MicroRNAs (miRNAs) and Twist1-induced epithelial-mesenchymal transition (EMT) in cancer cell dissemination are well established, but the involvement of long noncoding RNAs (lncRNAs) in Twist1-mediated signaling remains largely unknown." (PMID 31941509, 2020). "In addition, these studies imply that Twist1 downmodulates nuclear lamins that further alter spatiotemporal organization of the cancer genome and epigenome." (PMID 32337580, 2020). "Abnormal expression of Twist1 is frequently observed in many types of cancer." (PMID 33381597, 2020). "This suggests that CTDSP1 can potentially attenuate TWIST1 and antagonize cancer progression." (PMID 32397221, 2020). "In addition, we observed a significantly decrease of the expression level of phosphorylated p38MAPK, which has been reported to be a downstream signaling of Rho/ROCK signaling and regulate expression of Twist1 in various cancers." (PMID 31443665, 2019). "Moreover, Twist1 is found to overexpress in a variety of tumors and plays an important role in cancer initiation, progression and metastasis." (PMID 30973923, 2019). "Twist1 is upregulated by a variety of factors in cancer, including SRC-1, STAT3, HIF-1α and NF-κB." (PMID 30973923, 2019). "We also provided evidence that LUADT1 may sponge miR-15a-3p to upregulate Twist1, thereby promoting cancer cell invasion and migration." (PMID 31842825, 2019). "RUNX1 and TWIST1 and patients’ gender didn’t show a correlation with cancer-specific survival." (PMID 31655611, 2019). "Finally, in advanced carcinomas, we expected frequent TWIST1 cytoplasmic expression and co-expression with PRMT1." (PMID 31655611, 2019).
cancer (continued). "Previously, we discovered that Twist1 is highly expressed in cancer-associated fibroblasts (CAFs) but not in normal quiescent fibroblasts." (PMID 30069061, 2018). "Given that SNCG is a target of the oncogenic transcription factor Twist1, we then investigate whether SNCG acts downstream of Twist1 to promote cancer cell invasion." (PMID 29795373, 2018). "To validate whether Twist1 regulation is through AMPK activation, we next investigated the effects of AMPK inhibition on Twist1 expression in the epithelial-mesenchymal-transitioned cancer cells lines A549, MDA-MB-231 and MDA-MB-435S." (PMID 29950484, 2018). "SNCG knockdown abrogates TGF-β- or Twist1-induced cancer cell migration and invasion." (PMID 29795373, 2018). "Twist1 overexpression could further promote the cancer cell EMT process through regulating E-cadherin, N-cadherin, and MMP expression." (PMID 30021598, 2018). "SNCG knockdown inhibits the promotion of cancer metastasis by Twist1." (PMID 29795373, 2018). "Moreover, Twist1 promotes cancer metastasis by regulating multiple processes involved in metastasis, such as angiogenesis, invasion, migration, extravasation, and chromosomal instability." (PMID 29795373, 2018). "Twist1 also suppresses let-7i to induce the mesenchymal-type movement of cancer cells." (PMID 29685144, 2018). "SNCG promotes TGF-β- and Twist1-induced cancer cell invasion and migration." (PMID 29795373, 2018). "Twist1 activation is required for STS-mediated cancer cell progression." (PMID 28977889, 2017). "It is noteworthy that both groups used the same NSCLC cell line (A549) and drug (cisplatin) but obtained different results, implying that Twist1 might be able to mediate chemo-resistance through multiple down-stream pathways even in the same cancer type." (PMID 28099910, 2017). "Moreover, we revealed that Twist1 is a key regulator in the transdifferentiation from normal quiescent fibroblasts to CAFs using cancer tissue derived ex vivo CAF cultures." (PMID 29029429, 2017). "Twist1 expression in esophageal fibroblast facilitates the migration and invasion of cancer cells." (PMID 29029429, 2017). "This may both highlight the impact of TWIST1 on OCT4 expression and introduce a novel link between TWIST1 and the stemness state of cancer cells." (PMID 29299035, 2017). "Such linkage may expand our understanding of the biological role of TWIST1 in cancer cell progression and self-renewal." (PMID 29299035, 2017). "More importantly, we put special emphasis on revealing the molecular basis of the correlation between Twist1's diversified biological functions, piecing together the whole delicate picture of Twist1's multiple roles in various cancers and providing new directions for future research." (PMID 28099910, 2017). "EMT is also believed to have an important role in tumor invasion and metastasis, with TWIST1 upregulation enhancing this ability in different types of cancer cells including melanoma, nasopharyngeal carcinoma, ESCC, and breast, uterine, prostate, pancreatic, gastric and cervical cancers." (PMID 29299035, 2017). "In summary, our study raised a novel mechanism for developing of EMT in the presence of Bcl-2 and cancer progression mediated by a Bcl-2/Twist1 functional complex, which may provide a new therapeutic target for OSCC treatment." (PMID 28032603, 2017). "Overexpressed TWIST1 can be correlated with upregulation of the cancer stem cell marker OCT4 and the protein may play critical regulatory role in OCT4 gene expression." (PMID 29299035, 2017). "This hypothesis is supported by the recent report of a genetic interaction between PRRX1 and TWIST1 to promote cellular invasion during embryogenesis and in cancer cells." (PMID 28769044, 2017). "Furthermore, Twist1 acts together with Bmi1 to suppress the expression of let‐7, a microRNA expressed during stem cell differentiation, leading to cancer stemness." (PMID 28649800, 2017).
cancer (continued). "Hypoxia induces the expression of Twist1 or Snail to promote EMT during cancer progression." (PMID 28649800, 2017). "Indeed, the migration and invasion of TE11 cancer cells were significantly increased by CM from Twist1-expressing fibroblasts compared to control fibroblasts." (PMID 29029429, 2017). "However, we postulate that miR-210-3p levels determine cancer cell migration and/or invasion due to its effects on TWIST1 that promotes EMT." (PMID 28152509, 2017). "We further demonstrate that a WR domain mimetic can abrogate TWIST1 activity in vitro, providing further evidence that blocking this interaction and inhibiting TWIST1 expression could be an effective cancer therapeutic strategy." (PMID 28283022, 2017). "Activation of NF-κB pathway is associated with Twist1 expression and EMT in cancer cells." (PMID 28774312, 2017). "TWIST1 is one of the regulators which promote EMT pathway in many cancers." (PMID 28460469, 2017). "Twist1, a basic helix‐loop‐helix transcriptional factor, is a master regulator of gastrulation and mesoderm specification and is recently demonstrated to be essential to mediate cancer metastasis." (PMID 28649800, 2017). "Interestingly, Twist1 expression in stromal fibroblasts was positively correlated with Twist1 expression in cancer cells (χ2 = 4.015, r = 0.154, P = 0.045)." (PMID 29029429, 2017). "Twist1 is a master regulator of epithelial mesenchymal transition and carcinoma metastasis." (PMID 29296200, 2017). "Further investigations of WR-mediated binding interactions and development of TWIST1-targeted therapies may be of great value to patients suffering from advanced, drug resistant carcinomas." (PMID 28283022, 2017). "Determining the cellular machinery responsible for TWIST1 protein turnover in EOC may shed light not only on its regulation in other cancers undergoing EMT, but also on its regulation during mesodermal development." (PMID 27876874, 2016). "In addition, to investigate the effect of Twist1 on cancer progression according to MSI status, we evaluated cell migration and cell invasion in MSS LS513 and MSI LoVo cells." (PMID 27494849, 2016). "Given the implications of EMT in many different tissues and cancer types, we set out to test whether combining exogenous TGFβ treatments with activation of Twist1 also boosts the EMT process in other cellular systems than the human breast." (PMID 27105506, 2016). "TLR4 activation may also activate TWIST1 and promote the formation of stem-like cancer cells in the mouse liver via a cooperation with nanog and STAT3." (PMID 28116318, 2016). "In this study, we demonstrated that TTP down-regulates Twist1 and Snail1 expression in cancer cells, suggesting the possibility that TTP may inhibit the expression of EMT marker genes through enhancing the degradation of Twist1 and Snail1 mRNAs." (PMID 26840564, 2016). "Overexpression of Twist1 can lead to solid tumor formation and metastatic disease in cancer." (PMID 27023622, 2016). "TWIST1, a transcription factor, plays a pivotal role in cancer initiation and progression." (PMID 27661106, 2016). "A deeper understanding of EMT signalling may allow for the identification of additional novel therapeutic targets and strategies, in addition to reduction of TWIST1 itself, for the most aggressive types and subtypes of ovarian and other cancers." (PMID 27876874, 2016). "Activated STAT3 can directly bind to the promoter of Snail or Twist1 to induce EMT in cancer cells." (PMID 27121055, 2016). "But so far, the molecular mechanism of Twist1 gene on angiogenesis in human cancers remains unknown." (PMID 26823670, 2016). "Recently, some miRNAs were identified to modulate cancer properties by directly targeting TWIST1 expression in different cancer cells, suggesting that TWIST1 might be regulated by different miRNAs during cancer progression." (PMID 27930738, 2016).
cancer (continued). "Moreover, SNAIL1 and TWIST1 expression levels are positively correlated with increased micro-vessel density in cancers, where TWIST1 expression is positively correlated with cancer angiogenesis and invasiveness." (PMID 27335258, 2016). "TWIST1 contributes to cancer metastasis by promoting an epithelial-mesenchymal transition (EMT)." (PMID 27930738, 2016). "Basic helix-loop-helix transcription factor Twist1 is a master regulator of Epithelial-Mesenchymal Transition (EMT), a cellular program implicated in different stages of development as well as metastatic dissemination of carcinomas." (PMID 27105506, 2016). "Up-regulation of TWIST1/N-cadherin/NF-kappaB pathway makes cancer more resistant to metformin." (PMID 26359363, 2015). "Thus, it is very important to clarify the transcriptional regulatory mechanisms for Twist1 in cancer cells." (PMID 26695186, 2015). "In order to further explore the mechanisms about how metformin regulates N-cadherin, we evaluated protein expression of TWIST1 in PC3 and T24 cancer cells after treatment with metformin and found that expression of TWIST1 was closely correlated with expression of N-cadherin." (PMID 26359363, 2015). "Interestingly, Akt pathway or Wnt pathway are directly related to the TWIST1 pathway in the progression of cancer metastasis." (PMID 26023736, 2015). "In addition to the overexpression, epigenetic changes, especially promoter methylation of TWIST1 gene, are also involved in cancer metastasis." (PMID 26023736, 2015). "Twist1 has been shown to mediate cancer migration through triggering Rac1 activation." (PMID 25868853, 2015). "Moreover, in high-grade budding cancers an inverse correlation between TWIST1 methylation and stromal protein expression was observed, suggesting hypermethylation as a mechanism of TWIST1 regulation." (PMID 25806371, 2015). "We speculated that TQ treatment decreases the expression of TWIST1 and its downstream protein N-Cadherin in cancer cells, while SNAIL1 and Vimentin were partially affected in cell specific manner." (PMID 26023736, 2015). "Moreover, we also suggest that TWIST1 is an upstream molecule of N-cadherin/NF-kappaB signaling and manipulation of TWIST1 expression changes the sensitivity of cancer cells to metformin." (PMID 26359363, 2015). "Transcriptional factor, Twist1, was shown to regulate cancer cell migration and invasion." (PMID 25868853, 2015). "In addition to promoting EMT in cancer cells, TWIST1 is thought to promote the cancer stem cell (CSC) phenotype, inhibit apoptosis, and contribute to chemotherapy resistance." (PMID 25759817, 2015). "It should be noted that the potential upstream and downstream regulators of Twist1 in different contexts of cancer cells could vary, which requires further investigation." (PMID 26360779, 2015). "miR10b is a transcriptional target of Twist1 in cancer cells and is involved in repression of Hoxd10 expression, suggesting that Twist1 may regulate Hoxd10 expression via control of this miRNA." (PMID 24893291, 2014). "Extensive studies in previous years have focused on Twist1 and have identified correlations between the development of acquired metastatic ability, stem cell-like characteristics and chemoresistance in various human cancers." (PMID 24944676, 2014). "Interestingly, the target sites for miR-151-5p and miR-337-3p will still be present, even if the previously reported shortening of 3′UTRs in cancer cells also occurs with TWIST1 and either the first or the second pA signal should be used." (PMID 23741524, 2013). "Li and Zhou showed that activation of the AKT pathway by TWIST1 is critical for the sustention of cancer stem cell-like traits generated by EMT, again suggesting a link between loss of NKX3-1 expression, relive of TWIST1 expression and eventually activation of AKT pathway." (PMID 23368843, 2013). "It is intriguing to speculate about the insight these findings may provide into the role of TWIST1 in cancer." (PMID 23555309, 2013).
cancer (continued). "Overexpression of TWIST1 has been observed in various types of cancer such as breast, prostate, gastric, pancreatic and bladder cancer, hepatocarcinoma, rhabdomyosarcoma, and glioma and is often associated with more aggressive phenotypes, and acquired drug resistance." (PMID 23741524, 2013). "The basic helix-loop-helix (bHLH) transcription factor TWIST1 was previously demonstrated to be a potent promoter of cancer cell dissemination into circulation and metastasis, providing an ideal target for investigation and a promising therapeutic target for intervention." (PMID 22891766, 2012). "It has yet to be shown in vivo whether Twist1 plays a role in the initiation or maintenance of cancer." (PMID 22654667, 2012). "TWIST1 is a highly conserved developmental gene involved in embryogenesis that may be reactivated in cancers promoting both malignant conversion and cancer progression through an epithelial to mesenchymal transition (EMT)." (PMID 22272264, 2012). "TWIST1, an evolutionarily conserved basic helix-loop-helix (bHLH) transcription factor, is a strong promoter of metastatic spread and its expression is elevated in many advanced human carcinomas." (PMID 22891766, 2012). "The authors demonstrated that EMT in Ras-transformed HMLER cells, induced by overexpression of Snail1 or Twist1, led to the acquisition of cancer stem cell traits like increased mammosphere formation, breast CSC surface marker expression and most importantly, increased tumorigenicity in vivo." (PMID 24281177, 2010). "However, the commonality of genes regulated by TWIST1 in GBM cell lines and carcinoma metastasis suggested that the molecular program in GBM does partially overlap with that of TWIST1-mediated EMT in carcinomas." (PMID 20646316, 2010). "It was reported that Twist1 was involved in the metastasis of cancers that could induce EMT." (PMID 38528462, 2024). "In addition, EMT is a crucial step of cancer cell migration and invasion, we focused on the possible associations between P4HA3 expression and classic EMT markers, such as Vimentin (VIM), TWIST1, Snail2 (SNAL2), Snail1 (SNAL1), Fibronectin1 (FN1), and N-cadherin (CDH2)." (PMID 39504328, 2024). "Similarly, ALDH1A1 and TWIST1 are highly upregulated in cancer stem cells." (PMID 39334449, 2024). "Thus, Twist1 expression was sufficient to induce CCL2 in normal and cancer mammary epithelial cells, and the expression of Twist1 may account for the elevated CCL2 expression in BC cells with mesenchymal characteristics." (PMID 37208442, 2023). "It was hypothesized that TWIST1 reduces E-cadherin expression, which is a cell-to-cell adhesion molecule, and loss of its expression results in epithelial-to-mesenchymal transition (EMT), a hallmark of cancer." (PMID 37371512, 2023). "The knockdown of USP29 significantly decreased the expression of TWIST1, and increased cancer cellular sensitivity to these chemotherapeutic agents both in vitro and in vivo, which could be largely reversed by the reconstitution of TWIST1 in USP29‐depleted cells." (PMID 36782089, 2023). "TWIST1 may also relieve hypoxia via neovascularization, as described in multiple cancer types." (PMID 38139368, 2023). "Furthermore, TWIST1 play a key role in myogenesis and genetically or pharmacologically inhibition of TWIST1 could curb cancer-driven muscle cachexia and reduce morbidity and mortality." (PMID 36793601, 2023). "The Wnt signaling pathway also activates TWIST1—a member of the basic helix–loop–helix transcription factor family involved in cell differentiation and lineage determination, but that also facilitates cancer metastasis by acting as an EMT-inducing transcription factor." (PMID 35562862, 2022). "Finally, we examined the impact of TWIST1(K73R) on invasion and migration of the cancer cells." (PMID 36115849, 2022). "However, the functional role of the TCF4/TWIST1 complex in PTHrP-associated cancer cachexia has not been previously investigated." (PMID 35406121, 2022).